IL18 (interleukin 18)
Diseases named in the same sentence as IL18 in open-access papers (continued):
Sharing a sentence is not in itself a finding about the gene and the disease.
tumor (continued). "Among the best described immunostimulatory cytokines used in TRUCKs are IL-12 and IL-18, which have been shown to remodel the tumor microenvironment in several experimental systems by increasing the infiltration of inflammatory immune cells, such as M1 macrophages, NK cells, and T cells." (PMID 41181132, 2025). "The IL-18 fusion resisted interleukin-18 binding protein (IL-18BP) inhibition and exhibited a 10,000-fold reduction in activity while preserving cis-signaling and demonstrated strong efficacy across tumor models." (PMID 41488627, 2025). "Moreover, the cytokines IL-1 and IL-18 released during pyroptosis can promote tumor infiltration and increase the possibility of tumor development and metastasis." (PMID 39834603, 2025). "IL18 is described as a double-edged sword, exhibiting both anti-tumor and pro-tumor effects." (PMID 41257666, 2025). "In addition, NLRP3 activation in neutrophils induces IL-1β and IL-18 secretion, promotes chronic inflammation and enhances tumor growth." (PMID 41157253, 2025). "Furthermore, a decoy-resistant IL-18 that is resistant to inhibition via the IL-18 binding protein showed anti-tumor effects as a monotherapy and in combination with ICB therapy." (PMID 38391959, 2024). "Their antitumor functions include the production of reactive oxygen species, but in the later stages of tumor development, there is high infiltration of N2 neutrophils that support tumor growth and progression via the degradation of arginine, an activator of T cells, or suppress IL-18 production." (PMID 38542199, 2024). "Additionally, genes, associated with inflammasome and cell death including tumor suppressive TNF signaling pathways were upregulated in the samples treated with NT GSDMD + IL-1β + IL-18." (PMID 39737979, 2024). "We next compared these IL18-armored γδ CAR T cells in tumor re-stimulation assays." (PMID 38745414, 2024). "In particular, TREM2+ macrophages can prevent the recruitment and activation of NK cells by blocking the activities of IL-18 and IL-15 through the production of IL-18 binding protein and by inhibiting the production of IL-15 by tumor-infiltrating dendritic cells." (PMID 38426089, 2024). "During RT pyroptosis could lead to the release of immune factors such as IL-18 and IL-1β, which in turn facilitate the promotion of anti-tumor immunity." (PMID 38228635, 2024). "Mice with NLRP3 and caspase-1 deficiency subjected to AOM/DSS showed a dramatically increased tumor burden in the colon due to reduced IL-18 levels that altered the production and activation of the tumor suppressors IFN-γ and signal transducer and activator of transcription 1 (STAT1)." (PMID 39684769, 2024). "Also as expected, biologically active IL18 was detected when T cells expressing pCAR-H/T + GzB-IL18 were stimulated either on MDA-MB-468 tumor monolayers or by CD3+CD28 crosslinking." (PMID 38745414, 2024). "In patients that are resistant to checkpoint immunotherapy, targeting IL-18BP could release IL-18 from its complex, enabling it to exert its beneficial anti-tumor effects." (PMID 39769266, 2024). "Next, we undertook tumor re-stimulation experiments to assess whether these formats of IL18 delay the onset of functional exhaustion, indicated by failure to destroy ≥60% of tumor cells within each 72-h re-stimulation cycle." (PMID 38745414, 2024). "Additionally, treatment with IL-18/-21 enhances NK cell cytotoxicity, thereby highlighting its potential to promote anti-tumor effects." (PMID 38548803, 2024). "If this holds true, IL-2/IL-18-induced NK cells function as a bridge between innate immunity and adaptive immunity, challenging the conventional view of NK cells solely as innate immune effector cells that naturally eliminate tumor cells." (PMID 39195212, 2024). "Similarly, IL-18 and TNF-α, both implicated in tumour growth and angiogenesis, point to a complex network of cytokine interactions driving the progression from chronic inflammation to cancer." (PMID 38561502, 2024).
tumor (continued). "Moreover, pro-inflammation cytokines, such as Il1b, Il12b and Il18, were upregulated in the tumor of Il21r−/− mice; whereas anti-inflammation cytokines, including Il10 and Il22 were decreased in the tumor of Il21r−/− mice." (PMID 38720319, 2024). "The infection and subsequent lysis of tumor cells by oncolytic viruses lead to the release of proinflammatory molecule cascades into the TME, including type 1 interferons, DAMPs, PAMPs, IL-18, IL-1β, and also tumor antigens, generating robust antiviral and antitumor immune responses." (PMID 39066359, 2024). "In addition, we demonstrate that IMSA101-treatment increases IL-18 secretion which enhances CART anti-tumor efficacy." (PMID 38730243, 2024). "In order to investigate whether EEBR inhibits NSCLC progression in vivo via the NF‐κB‐NLRP3‐GSDMD pathway by promoting pyroptosis, we evaluated the levels of IL‐1β and IL‐18 in tumour tissues." (PMID 38214430, 2024). "Additionally, tumor cell pyroptosis leads to the release of a plethora of inflammatory and pro-inflammatory cytokines, notably IL-18." (PMID 39521987, 2024). "Choi and his colleagues also found that intratumoral injection of oncolytic adenovirus co-expressing IL-12 and IL-18 in B16F10 tumor bearing mice could enhance the infiltration of T cells and NK cells in the tumor, which conferred potent antitumor effects." (PMID 38548896, 2024). "eATP metabolism in the TME is required for tumor-supportive immune environment including increase of immunosuppressive myeloid cells and decrease of intratumor T cell activation, through blocking the tumor-suppressing eATP–P2X7R (an ATP-gated channel)–inflammasome–IL-18 pathway." (PMID 38786066, 2024). "Interestingly, IL-15, IL-18, and IL-1β cytokine profiles reveal a significant host serum increase after day 35 when the tumor began to progress in growth (respectively)." (PMID 39451257, 2024). "Notably, past reports have shown that stimulating NK cells with IL-12, IL-15, and IL-18 endows them with memory-like properties, better anti-tumor activity, and persistence." (PMID 38711506, 2024). "Pretreatment of NK cells with a combination of Interleukins-15 (IL-15) and IL-18 prior to cryopreservation improves NK cell recovery to ~90-100% and enables equal tumour control in a xenograft model of disseminated Raji cell lymphoma compared to non-cryopreserved NK cells." (PMID 38729924, 2024). "However, inactive IL-18 levels allowed to discriminate patients with a first tumor progression, assessed after 7 weeks of treatment, with worse overall survival." (PMID 38927931, 2024). "Therefore, altogether, high tumor NLRC4 expression tracks with immune infiltration, including DCs and T cells, independently of tumor IL-18 variation, and this is consistent with better clinical survival of patients." (PMID 38652550, 2024). "The residual RP116 and IL-18/-21-pretreated eNK cells showed anti-tumor effects on BCC." (PMID 38548803, 2024). "The results of the IL-18 antibody group may be due to the dual role of IL-18 in tumor growth in the in vivo model, and its potential regulation by other pathways." (PMID 39230586, 2024). "IL-18 has also exhibited therapeutic effects in tumor treatment." (PMID 39221244, 2024). "Bregs interact with PDAC cells, and tumor cells release IL-18 to promote the production of Bregs." (PMID 38590651, 2024). "Immunofluorescence staining confirmed that the expression of chemokines CCL3, CCL4 and CCL5 and the cytokines IL-12, IL-15 and IL-18 by KCs in the liver of Clec4fcreId3f/f mice was reduced or abolished at the tumour margin and in the tumour in comparison to in the littermate controls." (PMID 38326607, 2024). "Salmonella Typhimurium has been used in immunotherapies in murine trials, with significant tumor reduction, resulting from the local expression of bacteria or the expression of immune system-stimulating molecules on tumor cells IL-18, CCL21, LIGHT, or the Fas ligand." (PMID 39594765, 2024).
tumor (continued). "Finally, in an autologous setting, we corroborated that patient-derived iTRUCK19.18 cells exhibited enhanced efficacy in eliminating the same-patient tumor B cells only when IL-18 is induced by Dox (second-right bar)." (PMID 39640015, 2024). "CAR T cells engineered to secrete IL-18, demonstrated improved anti-tumor efficacy." (PMID 38391959, 2024). "Given that IL18 has also been reported to boost anti-tumor activity of human γδ T cells, we next set out to test whether GzB-IL18 armoring could be used to potentiate pCAR-H/T+ γδ T cells." (PMID 38745414, 2024). "These mice also showed accelerated tumor growth and reduced IL-18 levels in tissues." (PMID 39456655, 2024). "In addition, IL-18 evades the anti-tumor immune response, as reflected by the potential immunosuppressive role of IL-18 in NK cell-controlled tumors." (PMID 38553639, 2024). "The release of pro-inflammatory cytokines such as IL-1β and IL-18 can promote tumor growth and angiogenesis, while sustained inflammation may lead to immune suppression, hindering effective anti-tumor responses." (PMID 39769450, 2024). "Pharmacological inhibition of NLRP3 inflammasome using MCC950, followed by PTX administration decreased the pro-inflammatory processes associated with anti-tumor treatment as indicated by the expression of NLRP3, caspase-1, IL-1β and IL-18, compared with PTX treatment." (PMID 39433537, 2024). "Thirdly, IL-18 facilitates the infiltration of immune cells, particularly T cells and NK cells, into the tumor microenvironment, thereby enhancing the overall immune response against the tumor." (PMID 38957317, 2024). "IL‐1β and IL‐18 are initiating anti‐tumour immune indispensable core players." (PMID 38652105, 2024). "Furthermore, ectopic expression of ID3 in hiPSC-Macs also increased their production of the chemokines CCL3, CCL4 and CCL5, and the cytokines IL-12, IL-15 and IL-18 in response to tumour cells in vitro." (PMID 38326607, 2024). "Besides, Elisa results of tumor tissue displayed that compared with tumor model group, the levels of IL-1β and IL-18 in XRZYBXD high dose group were increased." (PMID 40046008, 2024). "However, IL-18 also displays anti-tumor ability to inhibit the growth and metastasis of many types of tumor cells by activating the immune response of CD4 + T cells and/or NK cells in the TME." (PMID 38553639, 2024). "Consequently, efforts have been made to regulate IL18 release in an activation-dependent manner, thereby conferring tumor-dependent spatiotemporal control over its biological activity." (PMID 38745414, 2024). "Moreover, IL-18 can regulate the expression and activity of apoptosis-related proteins, potentially promoting apoptosis and inhibiting tumor growth." (PMID 39267832, 2024). "Additionally, M1 macrophages secrete a series of anti-tumor factors, such as cytokines IL-12 and IL-18, thereby inhibiting tumor growth." (PMID 38762523, 2024). "Having seen that the IL-18 pathway may be primed for reactivation in ccRCC, we next performed tumor growth and survival analyses in 2 syngeneic, immunocompetent murine RCC models: Renca and RAG." (PMID 39561007, 2024). "Additionally, we observed that usenamine A increased ROS levels in tumor tissues and elevated levels of IL-1β and IL-18 in serum (p < 0.01)." (PMID 38265972, 2024). "Similarly, immunofluorescence staining in tumoural liver 2 weeks after intraportal injection of KPC cells in wild-type mice indicated that CCL3, CCL4 and CCL5, and IL-12, IL-15 and IL-18 are most prominently produced by KCs present at the tumour margin." (PMID 38326607, 2024). "The specific mechanism of action and effects of IL-18 may be influenced by various factors, including tumor type, tumor microenvironment, and immune status." (PMID 39267832, 2024). "IL-23/IL-18-polarized neutrophils have an impact on tumor- and collagen-induced arthritis in mice." (PMID 38137369, 2023).
tumor (continued). "Furthermore, it also decreased the expression of proinflammatory cytokines (IL-1beta and IL-18) and decreased MDSC and tumor-associated macrophage levels in the TME." (PMID 37513979, 2023). "To clarify the relationship of IL18 expression and promoter methylation with the key molecules participating in the anti-tumor immune responses, we explored the relationship between IL18 expression and promoter methylation and 74 key immunomodulators using the TCGA cohort." (PMID 36707882, 2023). "In addition, the OM group had significantly reduced expression of Toll-like receptors (TLR4) and IL-18 relative to the OL group, contributing to the tumor’s immune escape." (PMID 38260202, 2023). "The NLRP1 inflammasome has also been studied in the TME of multiple myeloma, where NLRP1 increases the production of MDSCs by sensing disturbances in hematopoietic stress or cellular homeostasis and responding by secreting IL-18, which leads to accelerated tumor progression." (PMID 37497237, 2023). "Furtherly, IL-18 expression in CAFs and tumour cells of NSCLC was detected." (PMID 37871286, 2023). "When an immune‐suppressing microenvironment is established, IL‐18 boosts tumor growth even further." (PMID 37752941, 2023). "Furthermore, we previously reported the effectiveness of the combination of IL18 and immune checkpoint inhibitors in suppressing tumor metastasis." (PMID 38139000, 2023). "Furthermore, we recapitulate our current knowledge of the production of IL-18 downstream of P2RX7 activation and how IL-18 controls the fate of tumor growth." (PMID 37298187, 2023). "Inflammasome components can be expressed and activated by various stimulators in cancer cells, fibroblasts, and macrophages resulting in the secretion of IL-1β and IL-18, which further modulates the expression of PD-L1 in tumor cells and recruitment of immune-suppressive cells in TME." (PMID 36932407, 2023). "Considering that inflammasomes may initiate pyroptosis in tumor cells and that IL-1β and IL-18 have been shown to activate T cells and NK cells, inflammasome activators may improve the effects of immune checkpoint inhibitors." (PMID 36932407, 2023). "On the one hand, pyroptosis can secrete IL-1β and IL-18 to trigger inflammatory responses and recruiting immune cells, which might enhance the anti-tumor effects of immunotherapy." (PMID 36941988, 2023). "Subsequently, these authors engineered a variant of decoy-resistant IL-18 (DR-18) that does not bind the decoy receptor IL-18BP and retains the ability to bind tumor-infiltrating lymphocytes." (PMID 37483629, 2023). "IL-18 is essentially a pro-inflammatory cytokine that activates NF-κB, and it has a dual effect in tumor progression: it can activate immune responses and eliminate cancer cells, whereas higher levels of IL-18 promote angiogenesis, metastasis, proliferation and immune escape." (PMID 38201482, 2023). "Lrrc8e and Il18 may be positively correlated; however, further study is warranted to determine whether IL18 can promote or suppress the growth of these tumor types." (PMID 38139000, 2023). "The effector cytokines of inflammasomes can be different when it comes to spontaneous breast cancer mice models where genetic blockage of IL-1α/IL-1R1 signal develops higher tumor burden and increased mortality rate implying similar roles of IL-1α, IL-1β, and IL-18 in tumorigenesis." (PMID 36932407, 2023). "Among them, IL18 has been shown to play a role in carcinogenesis and tumor progression." (PMID 36975376, 2023). "This characteristic may make IL-18 to be a promising candidate to improve anti-tumour efficacy of T cells." (PMID 37871286, 2023). "Interleukin 18 is produced mainly by macrophages and may mediate an anti-tumour immune response, and also induces the secretion of gamma interferon." (PMID 37847180, 2023). "CASP4, CASP6, CASP8, IL18, and PYCARD were associated with clinical stage, which means that IL18 and PYCARD may be involved in tumor progression." (PMID 36882663, 2023).
tumor (continued). "To investigate this further we engineered AT3ova and MC38 tumor cells to express IL-18." (PMID 37914685, 2023). "According to previous studies, IL‐18 activation may be a double‐edged sword that promotes tumor development and progression." (PMID 35789548, 2023). "Besides IL-1β, IL-18 secreted by tumor cells through NLRP3 is positively correlated with PD-L1 expression and negatively correlated with cytotoxic T cells." (PMID 36932407, 2023). "Similarly, the functional relevance and mechanisms of XIST in inhibiting tumor suppressive cytokine/chemokines (i.e., IL-7, IL-15, and IL-18) need to be determined." (PMID 36922677, 2023). "However, another research has found that NSCLC-derived IL-18 stimulates anti-tumor IFN-γ production from a minor part of CD8+ T cells (T-bet+Eomes+) that expresses a high level of IL-18R." (PMID 36932407, 2023). "For instance, some studies suggest that the anaplastic lymphoma kinase (ALK) inflammasome component is required for NLRP3 activation in macrophages and that NLRP3 inflammasome activation might play a pro-tumor role through the IL-18 effector cytokine." (PMID 37205092, 2023). "IL-18 takes a significant role in tumor growth, angiogenesis, invasion, and metastasis." (PMID 37705746, 2023). "In oral squamous cell carcinoma (OSCC), the serum levels of IL18 increase during tumor growth." (PMID 38139000, 2023). "Moreover, the emerging insights into the antitumor immunity effects of IL-18 were facilitated by the reduction of tumorigenesis, macrophage activation, inhibition of tumor angiogenesis, and induction of tumor cell apoptosis." (PMID 36742134, 2023). "On the one hand, pyroptosis is accompanied by IL-1β and IL-18 release, which could mediate tumor-promoting inflammation." (PMID 36941988, 2023). "IL-10, IL-18, and inflammasome expression levels were assessed in the tumor tissues." (PMID 37528154, 2023). "In line with this, it has been shown that the processing of IL-18 from ovarian tumor cells can be defective, which could explain its pro-tumoral activity when released from tumor cells." (PMID 37298187, 2023). "In addition to enhanced activation of the CAR T cells themselves, endogenous tumor-infiltrating lymphocytes (TILs) were more activated in the presence of IL-18." (PMID 36951942, 2023). "We found IL18 was highly expressed in RCC tumor tissues compared to normal tissues." (PMID 36707882, 2023). "Some groups reported that mice with deficient inflammasome components were more susceptible to CRC than the control group, and showed accelerated tumor growth proportionally to attenuated levels of IL-1β and IL-18, the latter mediating NK cell tumoricidal activity." (PMID 37891577, 2023). "In Il18−/− mice, the expression of Samsn1 is significantly decreased, suggesting that tumor growth might be promoted." (PMID 38139000, 2023). "IL-18BP, a binding protein targeting IL-18, limits anti-tumor immunity." (PMID 36932407, 2023). "Immune cells can also directly influence the phenotype and function of tumor vessels through various cytokines, such as cytokines that inhibit tumor angiogenesis (interferon-α, interleukin-12, interleukin-18 or tumor necrosis factor) and chemokines (CXCL9, CXCL10 or CCL21)." (PMID 36569915, 2022). "Several novel methods aiming to improve the anti-tumor effects of IL-18 have been developed." (PMID 35739593, 2022). "DAMPs then activate inflammatory reaction pathways, lymphocytes, monocytes and macrophages release IL-1 and IL-18 inflammatory regulating cell factors, promoting tumor antigens presentation for induction of T cells adaptive responses, which improves tumor immune escape." (PMID 35844515, 2022). "Moreover, IL-18 induced MDSCs to infiltrate into the tumor parenchyma in an OS model, suggesting an IL-18 inhibitor as a potential strategy in MDSC-targeted immunotherapy in patients with OS." (PMID 36311748, 2022).